CKAP5 (cytoskeleton associated protein 5)
Diseases named in the same sentence as CKAP5 in open-access papers:
CKAP5 is named in the same sentence as 25 diseases in open-access papers, as found by Europe PMC text mining. Sharing a sentence is not in itself a finding about the gene and the disease. The quoted sentences say what the papers report.
breast carcinoma (5 papers, 2018 to 2025). "Interestingly, high expression of the Snord67 host gene CKAP5 was associated with significantly worse overall survival in HER2-enriched breast cancer, consistent with previous results showing that CKAP5 expression is associated with poor prognosis in non-small cell lung cancer." (PMID 40316533, 2025). "The top three proteins (CKAP5, AURKA, and CDC20) interacting with TACC3 were verified by immunoprecipitation in breast cancer cells, and CKAP5, AURKA, and CDC20 were detected in the immunoprecipitation of anti TACC3 antibody." (PMID 34149795, 2021). "Notably, Snord67 and CKAP5 expression were highly correlated in breast cancer patients." (PMID 40316533, 2025). "Although we have shown in several models that loss of Snord67 impacted phenotypes independent of CKAP5 host gene expression, the correlation of Snord67 and CKAP5 expression in breast cancer patients raises the possibility that Snord67 expression may be co-regulated with expression of its host gene." (PMID 40316533, 2025). "Therefore, the close interaction of TACC3 with CKAP5, AURKA, and CDC20 may suggest the role of TACC3 in the progression of breast cancer, although future mechanistic studies are needed to verify this possibility." (PMID 34149795, 2021).
glioma (4 papers, 2018 to 2022). A benign or malignant brain and spinal cord tumor that arises from glial cells (astrocytes, oligodendrocytes, ependymal cells). "Further studies have shown that ARHGEF16 activates RhoG and PI3K, contributing to apoptosis resistance in tumor cells, and interacts with CKAP5 to promote the proliferation and migration of glioma cells." (PMID 35680563, 2022). "The identification of CKAP5 as an ARHGEF16-interacting protein in this study suggests that regulation of spindle integrity is important for glioma cell proliferation and migration." (PMID 30305138, 2018). "To investigate the role of CKAP5 in the glioma-promoting functions of ARHGEF16, we knocked down CKAP5 while overexpressing ARHGEF16 in U87 glioma cells." (PMID 30305138, 2018). "In this study, we identified ARHGEF16 as a target gene of GLI2 that interacts with cytoskeleton-associated protein 5 (CKAP5) to regulate glioma cell migration and proliferation, thus promoting glioma progression." (PMID 30305138, 2018). "Cytoskeleton-associated protein 5 (CKAP5) was identified as an interaction protein of ARHGEF16, which is important for the stimulatory effects of ARHGEF16 on glioma cell migration and proliferation." (PMID 30305138, 2018). "Our results indicate that the GLI2/ARHGEF16/CKAP5 axis promotes glioma progression by enhancing tumor cell migration and proliferation and could therefore serve as a therapeutic target for glioma treatment." (PMID 30305138, 2018). "Thus, CKAP5 acts in conjunction with ARHGEF16 to promote glioma cell migration and proliferation induced by GLI2." (PMID 30305138, 2018). "Moreover, CKAP5 has been confirmed to be crucial for glioma cell migration and proliferation." (PMID 35902921, 2022).
colorectal cancer (2 papers, 2021 to 2022). A primary or metastatic malignant neoplasm that affects the colon or rectum. "Aurora A kinase, which regulates centrosome maturation and plus-ends for kinetochore attachments, and ch-TOG (CKAP5), a microtubule polymerase, are over-expressed in colorectal cancer cells." (PMID 34880347, 2021).
ovarian carcinoma (2 papers, 2023). A malignant neoplasm originating from the surface ovarian epithelium. "We identified a highly responsive chemo-resistant ovarian cancer cell line, in which CKAP5 silencing led to significant loss in EB1 dynamics during mitosis." (PMID 37018392, 2023). "Thus, all the sensitive ovarian cancer cell lines showed G2-M cell cycle arrest and increased multicentric spindle formation in response to CKAP5 down-regulation, which was associated with the loss of cell viability." (PMID 37018392, 2023). "Functional effects of CKAP5 silencing was evident by G2/M arrest and multicentric spindle formation in CKAP5-sensitive ovarian cancer cell lines, NAR, A2780, and SKOV3." (PMID 37018392, 2023). "Together, our results highlight the importance of CKAP5 as a therapeutic target for genetically unstable ovarian cancer and warrants further investigation into its mechanistic aspects." (PMID 37018392, 2023). "We demonstrate that cells with high genetic instability were selectively susceptible to CKAP5 depletion, among them the chemo-resistant NCI-ADR/Res (NAR) ovarian cancer cell line, which was found to be highly sensitive to this cellular manipulation." (PMID 37018392, 2023). "Overall, our data suggest that CKAP5 is a promising therapeutic target in genetically unstable ovarian cancer." (PMID 37018392, 2023). "Since ovarian cancer is diagnosed mostly at late stages, it will be of great interest to study the effects of CKAP5 silencing in late-stage ovarian cancer metastasis." (PMID 37018392, 2023). "All the ovarian cancer cell lines analyzed were sensitive to CKAP5 down-regulation." (PMID 37018392, 2023). "CKAP5 down-regulation led to G2-M cell cycle arrest in both ovarian cancer cell lines tested." (PMID 37018392, 2023). "CKAP5 is important for survival of ovarian cancer cells and might become a unique therapeutic target for other types of cancers." (PMID 37018392, 2023). "All the ovarian cancer cells tested in our study demonstrated sensitivity to CKAP5 silencing, and among them, the chemoresistant NAR cell line was also highly responsive to lethal effects of CKAP5 knockdown." (PMID 37018392, 2023).
rhabdomyosarcoma (2 papers, 2022). A rare aggressive malignant mesenchymal neoplasm arising from skeletal muscle. "The circZNF609 RNA interacts with HuR to stabilize CKAP5 (Cytoskeleton Associated Protein 5) mRNA, a cytoskeleton/mitosis-associated factor, in RD cells (embryonal rhabdomyosarcoma cell line)." (PMID 35884580, 2022).
head and neck cancer (1 paper, 2018). A primary or metastatic malignant neoplasm affecting the head and neck. "It is also necessary for the survival of head and neck cancer as well as lung cancer cells, and its expression level in liver cancer is an independent prognostic factor for both progression-free and overall survival, with a significant correlation between high CKAP5 level and poor prognosis." (PMID 30305138, 2018).
Infertility (1 paper, 2025). "The personalization of infertility care significantly improves with the incorporation of TUBB8, KIF11, and CKAP5 into the diagnostic framework of assisted reproduction." (PMID 40650169, 2025). "The elucidation of molecular pathways involving TUBB8, KIF11, and CKAP5 has transformative potential in the diagnosis and treatment of infertility, particularly in cases with unresolved oocyte maturation arrest and early embryonic developmental failure." (PMID 40650169, 2025). "This thorough study presents new insights into the molecular mechanisms of infertility in women with unresolved oocyte arrest syndromes, highlighting the essential roles of TUBB8, KIF11, and CKAP5 in oocyte maturation and early embryonic development." (PMID 40650169, 2025).
ischemic stroke (1 paper, 2019). A stroke disorder caused by obstruction of blood flow to the brain, due to thrombotic (local blood clot formation) or embolic (due to a blood clot or other material traveling from another site) event. "The CKAP5 rs10734548 polymorphism shows significant association with ischemic stroke phenotype." (PMID 31464655, 2019).
melanoma (1 paper, 2022). A malignant, usually aggressive tumor composed of atypical, neoplastic melanocytes. "To this end, we overexpressed CKAP5 to induce increased MT growth rates in noninvasive SK-Mel-19 and SK-Mel-173 melanoma cells to levels typically observed in the invasive melanoma cells." (PMID 36875714, 2022). "In addition, we also induced MT growth rates in noninvasive melanoma cells by overexpression of CKAP5 and used CM from these cells." (PMID 36875714, 2022).
migraine (1 paper, 2023). "Additionally, we note that many significant genes (e.g., AMBRA1, ATG13, ARHGAP1, CKAP5, LRP4, and DDB2) have been associated with migraine, headache, and proinsulin." (PMID 36808568, 2023).
non-small cell lung carcinoma (1 paper, 2022). A group of at least three distinct histological types of lung cancer, including non-small cell squamous cell carcinoma, adenocarcinoma, and large cell carcinoma. "Previous literature has uncovered the CKAP5 is linked to the poor prognosis of non-small cell lung cancer patients." (PMID 35902921, 2022).
schizophrenia (1 paper, 2023). A major psychotic disorder characterized by abnormalities in the perception or expression of reality. "Studies have shown that centriolar coiled-coil protein 110 (CCP110), cytoskeleton-associated protein 5 (CKAP5), disrupted in schizophrenia 1 (DISC1), and transforming acidic coiled-coil containing protein 3 (TACC3) are essential for oocyte microtubule polymerization and spindle assembly." (PMID 37240406, 2023).
tumor (15 papers, 2015 to 2024). "Several mitosis-associated genes, including AURKA, DLGAP5, TPX2, KIF11, and CKAP5, were overexpressed in tumor tissues, and associated with cell proliferation and poor OS." (PMID 36499051, 2022). "We show that circRNA zinc finger protein 609 (circZNF609) interacts with several mRNAs increasing the final protein levels, which in the case of the cytoskeleton-associated protein 5 (CKAP5) leads to a stabilized microtubule cytoskeleton and an enhanced tumor cell proliferation." (PMID 35434270, 2022). "The interaction between the circZNF609 and CKAP5 mRNA favors the binding of the human antigen R (HuR) to the CKAP5 mRNA, leading to a stabilized microtubule cytoskeleton and enhanced tumor cell proliferation." (PMID 39452835, 2024). "Cells of different tumour cell lines were reported to be arrested in metaphase and underwent cell death after silencing CKAP5." (PMID 38978053, 2024). "LNP-mediated silencing of CKAP5 showed substantial delay in tumor growth resulting in significantly increased survival in siCKAP5-LNP–treated group as compared to control groups (P < 0.0001)." (PMID 37018392, 2023). "We observed a significant reduction in tumor growth, which was corroborated by increased survival in CKAP5-silenced mice (P < 0.0001)." (PMID 37018392, 2023). "It was reported that CKAP5 directly binds to tubulin via its tumor-overexpressed gene (TOG) domains." (PMID 30647854, 2018). "The tumor-targeting ability of anti-CD38-LNPs was also validated in a xenograft MM mouse model, where specific delivery of cytoskeleton-associated protein 5 (CKAP5) siRNA to bone marrow-residing and disseminated MM cells and improved therapeutic outcomes were achieved." (PMID 38516300, 2023). "Moreover, although we chose to knock down the expression levels of CKAP5 protein in this study, advancing this new therapeutic option to the clinic may require choosing a more tumor‐specific target such as Bcl‐2 or Irf‐4." (PMID 37171801, 2023). "The overexpression of CKAP5 could promote the development of tumor." (PMID 33540684, 2021). "CircZNF609 interacts with CKAP5 transcripts to promote ELAVL1 binding to mRNA, stimulate mRNA levels and translation, enhance mRNA stability and lead to changes in microtubule (MT) dynamics, thereby induce tumor cell proliferation." (PMID 37152286, 2023). "While binding of T-DM1 with HER2 is critical for killing HER2-positive tumor cells, our data suggest that cytotoxicity induced by T-DM1 interaction with CKAP5 may preferentially damage normal cells/tissues where HER2 expression is low or missing to cause off-target toxicity." (PMID 30647854, 2018).
cancer (14 papers, 2014 to 2025). A tumor composed of atypical neoplastic, often pleomorphic cells that invade other tissues. "As the expression status of the human XMAP215 family member, CKAP5/ch-TOG is associated with a poorer prognosis in cancers, future work is necessary to understand how acetylation affects other XMAP215 family members, particularly in disease states." (PMID 36084134, 2022). "Another report demonstrated that circZNF609 directly binds to CKAP5 mRNA, increasing CKAP5 translation, regulating microtubule function in cancer cells, and supporting cell-cycle progression." (PMID 41170695, 2025). "Analysis of CKAP5 knockout cancer cells of multiple tissue origins shows that CKAP5 is preferentially essential in aneuploid, chromosomally unstable cells, and the sensitivity to CKAP5 depletion is correlated to that of CENP-E depletion." (PMID 38424231, 2024). "Complementarily, large-scale analyses of hundreds of human cancer cell lines revealed that aneuploid, chromosomally unstable cells are more sensitive to CKAP5 perturbation." (PMID 38424231, 2024). "Our human cancer cell line data analysis suggests that the interaction between CKAP5 and mitotic errors is bidirectional—not only does CKAP5 depletion lead to mitotic errors but chromosomally unstable cells are also more sensitive to CKAP5 depletion." (PMID 38424231, 2024). "For translation of CKAP5 as a therapeutic target for genetically unstable cancer cells in the clinic, in future, it will be important to check its therapeutic efficacy in syngeneic and in patient-derived xenograft mouse models." (PMID 37018392, 2023). "Despite widespread expression of CKAP5 in various cell types, it can be a promising cancer cell mitosis target due to the vulnerability of cancer cells with high genetic aberrations and cell cycle abnormalities." (PMID 37018392, 2023). "Overall, our efficacy results clearly show the vulnerability of cancer cells to CKAP5 silencing in vitro as well as in vivo." (PMID 37018392, 2023). "Our screening of 20 solid cancer cell lines demonstrated selective vulnerability of genetically unstable cancer cell lines in response to CKAP5 silencing." (PMID 37018392, 2023). "Given the oncogenic effects of some GEFs, it is in principle possible to target the oncogenic GEFs and CKAP5 for cancer therapy." (PMID 30305138, 2018). "Taken together, these results suggest that the functional link between CKAP5 and CENP-E is ubiquitous in cancer, and that highly aneuploid, chromosomally unstable cancers might be more sensitive to CKAP5 depletion." (PMID 38424231, 2024). "Overall, the cell line analysis supports the generalizability of our findings, and strengthens the notion that CKAP5 might be a synthetic lethality of chromosomally unstable, aneuploid cancer cells." (PMID 38424231, 2024). "The interaction site with CKAP5 mRNA overlaps the back-splicing sequence, thus enhancing the translation of CKAP5, regulating microtubule function and maintaining cell cycle progression in cancer cells." (PMID 36506086, 2022). "We observed that CKAP5 down-regulation led to loss of bipolar mitotic spindle formation, which was substantially more prominent in genetically unstable cancer cells as compared to genetically stable, CKAP5 nonresponsive cancer cells, or normal noncancerous control cells." (PMID 37018392, 2023). "Having established the importance of CKAP5 activity for recruiting CENP-E to KTs, and the functional consequences of its inhibition, we sought to explore whether CENP-E expression and essentiality were associated with chromosome instability and with those of CENP-E in human cancer." (PMID 38424231, 2024). "CKAP5 expression across various cancer cell lines has not been well documented." (PMID 37018392, 2023). "In addition, given the reported ability of cancer cells to develop resistance against targeted and nontargeted therapy, it would be of great relevance to explore combination therapies for CKAP5 siRNA–mediated efficacy." (PMID 37018392, 2023).
cancer (continued). "Follow-up of metaphase-arrested NAR cells post-CKAP5 silencing via live-cell imaging showed that all the cells that entered mitosis could not complete the process in the absence of CKAP5, irrespective of spindle abnormality, which resulted in cancer cell death." (PMID 37018392, 2023).
cardiovascular disease (2 papers, 2019). "In this study, we investigated functional relationship between three protein-coding genes genetically associated with cardiovascular disease, i.e., CDH13, SLC12A3, and CKAP5, and their intronic miRNAs using a data-driven approach." (PMID 31464655, 2019).
CKAP5 also shares sentences with these, for which no sentence is quoted: colon cancer (2 papers); triple-negative breast carcinoma (2); aneuploidy (1); breast invasive carcinoma (1); Cirrhosis (1); heart failure (1); leukaemia (1); liver cancer (1); lung carcinoma (1); Zinc deficiency (1).